INS (insulin)
Diseases named in the same sentence as INS in open-access papers (continued):
Sharing a sentence is not in itself a finding about the gene and the disease.
diabetes (continued). "Diabetes mellitus (DM) is a chronic metabolic disorder resulting from complicated interactions of genetic, immunological, and environmental factors, leading to elevated blood glucose levels due to insufficient insulin production, resistance to insulin action, or both." (PMID 39803090, 2024). "Pioglitazone, a therapeutic drug for diabetes, could reduce the values of VSR in patients with diabetes, thereby increasing the sensitivity of tissues to insulin and glycemic control." (PMID 39400628, 2024). "In the context of hBMSCs, it has been reported that transplantation of hBMSCs elevated plasma and islet insulin contents in non-obese diabetic (NOD) mice with severe diabetes." (PMID 39468609, 2024). "An 18-year-old female was seen in the adolescent diabetes clinic, having been recently diagnosed with diabetes not requiring insulin therapy." (PMID 39329041, 2024). "In this study, we assessed glucose tolerance, insulin secretion, and insulin sensitivity in community-dwelling older adults without a history of diabetes using a 75-g oral glucose tolerance test (OGTT)." (PMID 38188453, 2024). "Diabetes in dogs closely resembles type 1 diabetes in humans, with most of the affected animals showing no detectable levels of insulin and pancreatic analysis typically reveals a total absence of islets." (PMID 39591292, 2024). "Two studies described the dietary quality of those classified with diabetes compared with healthy individuals, and none focused on individuals that use insulin." (PMID 39458437, 2024). "Diabetes is subdivided into insulin-dependent (type 1, T1DM) and non-insulin-dependent (type 2, T2DM) clinical forms." (PMID 39201799, 2024). "Among those who were not on any diabetes medicines, an oral glucose tolerance test was conducted to measure glucose and insulin levels." (PMID 38585953, 2024). "We describe a female patient who presented with glucose intolerance at the age of 31 years and who subsequently progressed to gestational and early-onset insulin-independent, anti-islet-antibody-negative non-obese diabetes." (PMID 38366195, 2024). "Diabetes mellitus (DM) is a chronic metabolic disorder characterized by either the insufficient production of insulin by pancreatic beta cells or the ineffective utilization of insulin by the body’s cells, resulting in elevated blood glucose levels and chronic inflammation." (PMID 39770852, 2024). "Diabetes is a chronic condition, which occurs when the body does not produce enough insulin or cannot use it in an effective away." (PMID 38525337, 2024). "Incretin action of GIP is dramatically reduced in the presence of diabetes, as demonstrated by the evidence that glucose-dependent insulin secretion is not potentiated by GIP administration in subjects with diabetes." (PMID 38831203, 2024). "While the intended purpose of CGM systems is glucose monitoring and that of insulin pumps is insulin delivery, the intended use of automated insulin delivery (AID) systems is diabetes management as driven by an AID algorithm, the accuracy of insulin delivery and input by the CGM system." (PMID 38041737, 2024). "Insulin is the preferred treatment for diabetes during pregnancy; however, there is no substantial evidence to recommend the best insulin regimen." (PMID 40071056, 2024). "For insulin-adjusted IVGTT AUC, there was a main effect of diabetes (F = 23.52, p < 0.0001) and training (F = 5.078, p < 0.05), and a significant interaction between diabetes and training (F = 5.072, p < 0.05)." (PMID 38435452, 2024). "Type 2 diabetes mellitus (T2DM) is a common metabolic disorder characterized by the combination of defective insulin secretion and the inability of insulin-sensitive tissues to respond appropriately to insulin." (PMID 39347127, 2024). "Diabetic ketoacidosis (DKA) is another serious complication of diabetes, which can occur when the body does not have enough insulin to break down glucose for energy." (PMID 38425638, 2024).
diabetes (continued). "Only adults taking insulin and those receiving no pharmacological treatment for diabetes maintained a stable weight on average." (PMID 38296356, 2024). "Although therapeutic approaches aimed at improving insulin delivery and glucose uptake are necessary for the treatment of diabetes, they are not designed to target the disease at its root cause, i.e., β-cell dysfunction or loss." (PMID 38891081, 2024). "The DIATEC trial will show the glycaemic and clinical effects of in-hospital CGM handled by in-hospital diabetes teams with access to operational insulin titration algorithms in non-critically ill patients with type 2 diabetes." (PMID 38711112, 2024). "Medications that increase sensitivity to insulin have been used for years in people with diabetes and are now being considered in people without diabetes to improve brain health." (PMID 40604159, 2024). "Access to a diabetes nurse, but not support staff with diabetes course, increased the likelihood of timely basal insulin-initiation." (PMID 38116986, 2024). "It should be noted that in all cited studies insulin was shown to be independent predictor of mortality regardless of the age, sex, diabetes duration and gylcemic status." (PMID 38538694, 2024). "These adverse effects of GK-GKRP disruption may be particularly relevant to patients with diabetes, who are prone to develop dyslipidemia, notably high TG and low HDL-C, due to insufficient insulin action." (PMID 38951793, 2024). "The siblings are currently on insulin at a full replacement dose and have no additional complications related to their diabetes." (PMID 38634869, 2024). "Diabetes mellitus is a chronic disease that occurs when the pancreas does not produce enough insulin or when the body cannot effectively use the insulin it produces, leading to elevated blood glucose levels." (PMID 39435211, 2024). "Recent reports suggest that Pasireotide-induced diabetes is mediated by a rapid impairment of insulin secretion without different insulin sensitivity, especially in older acromegalic patients with poor baseline glycemic control." (PMID 37344722, 2024). "The laboratory values and severity of diabetes are not known, but insulin use and the duration of diabetes are considered to be surrogate markers for the stage of diabetes." (PMID 39200117, 2024). "This is in line with our results as all the patients with type 2 diabetes included in our study presented good diabetes control and none of them were on insulin treatment." (PMID 38758998, 2024). "For 100 years, the Intravenous glucose tolerance test (IVGTT) has been used extensively in researching the pathophysiology of diabetes mellitus and AIRg—the IVGTT-induced acute insulin response to the rapid rise in circulating glucose—is a key measure of insulin secretory capacity." (PMID 38548796, 2024). "Diabetes is a chronic disease that occurs when blood glucose levels are exacerbated because the body does not produce enough insulin or because this hormone does not work effectively." (PMID 39478960, 2024). "Even though insulin is a necessity for survival, it is not the only factor contributing to good diabetes management." (PMID 39303284, 2024). "Diabetes mellitus (DM) is a common endocrinopathy in cats, with 80% of cats considered to have a disease comparable to type 2 diabetes mellitus (T2DM) in humans, characterized by insulin resistance (IR) and decreased insulin secretion." (PMID 39684905, 2024). "Many patients with type 2 diabetes mellitus (T2DM) do not achieve the desired glycaemic control despite being treated with insulin." (PMID 38694587, 2024). "AGE supplementation significantly increased fasting insulin AUC compared to the diabetes group without supplementation (p < 0.01)." (PMID 38778421, 2024). "The American Diabetes Association (ADA) and the European Association for the Study of Diabetes (EASD) have not yet included recommendations specific to this insulin formulation in their guidelines." (PMID 38172995, 2024).
diabetes (continued). "Administration of the SGLT2 inhibitor, DWP16001, can be an adjunctive method for managing diabetes in terms of glycaemic control without adverse effects in diabetic dogs receiving insulin therapy." (PMID 38686463, 2024). "Diabetes mellitus (DM) is a serious, chronic disease that occurs either when the pancreas does not produce enough insulin or when the body cannot effectively use the insulin it produces." (PMID 38371649, 2024). "Glycemic control has remained stable or improved during 2012–2019 despite an aging demographic during a period when many new insulin and noninsulin diabetes medications became available." (PMID 38273701, 2024). "However, increasing the hydrodynamic size of the insulin, such asinsulin peglispro, or bindingacylated insulins to HSA, such as IDeg, can eliminate the need for insulin dose adjustments in diabetes patientswith CKD." (PMID 38224978, 2024). "The present study results are consistent with those of a previous clinical trial, demonstrating that treatment with 365 mg/day of Mg2+ for six months remarkably improved fasting insulin and IR in individuals without diabetes." (PMID 39202546, 2024). "Diabetes mellitus is a serious and common disease that happens when insulin is not secreted by the pancreatic beta cells or when systemic cells are insulin resistant." (PMID 39000600, 2024). "Type 1 diabetes mellitus (DMT-1) is a metabolic disorder, mainly of autoimmune origin, characterized by hyperglycemia caused by a complete lack of insulin secretion." (PMID 38999837, 2024). "Insulin is however known to hold the potential to render cells insulin resistant over culture periods making insulin or insulin-containing ITS supplementation unsuitable for a diabetes research model." (PMID 38690930, 2024). "In the current study, a new diabetes subgroup, MIDD, was identified, which had lower HOMA‐β (only higher than the SIDD subgroup but significantly lower than the other subgroups), suggesting insufficient insulin secretion." (PMID 39136497, 2024). "recently reported an RI for serum insulin concentrations in 1,434 "healthy" Chinese men without diabetes (age range 20-69 years) of 1.57-16.32 μU/mL (9.42-97.9 pmol/L)." (PMID 39529982, 2024). "Inhibitors of the protein tyrosine phosphatase 1B (PTP1B), a negative regulator of the insulin signalling pathway, have emerged as a promising target for diabetes, but none have yet reached the market." (PMID 38786601, 2024). "The findings highlight the critical role of insulin in preserving muscle mass and quality, irrespective of diabetes duration, metabolic control, or age." (PMID 39058051, 2024). "Since 2019, thirteen keywords, including “mortality,” “mitochondrial biogenesis,” “diabetes mellitus,” “vitamin D,” “cells,” “TNF-α,” “muscle mass,” “mechanisms,” “injury,” “insulin resistance,” “resistance,” “autophagy,” and “protein,” have begun to emerge prominently." (PMID 39588187, 2024). "Insulin offered hope for extending the lives of children with diabetes, who at that time typically lived no more than a few months or years." (PMID 39718705, 2024). "The amount of DME and RT in peripheral sectors was independent of systemic factors such as BMI, duration of diabetes, duration of insulin intake, and HbA1c levels." (PMID 39064281, 2024). "Specifically, our research demonstrates that insulin and rosiglitazone, while used in the treatment of diabetes, do not exhibit the capacity to stave off the reduction in heel BMD." (PMID 38451994, 2024). "Type 2 diabetes mellitus (T2DM) is a metabolic disorder characterized by chronic hyperglycemia, primarily stemming from insulin resistance in peripheral tissues or inadequate insulin secretion from pancreatic islet β cells." (PMID 38495787, 2024). "Despite the absence of diabetes-related autoantibodies, the patient had extremely low levels of insulin and C-peptide release." (PMID 38247005, 2024).
diabetes (continued). "Another pooled study evaluated 1623 clinically healthy individuals aged 30–60 years old from The Relationship between Insulin Sensitivity and Cardiovascular Disease Study (RISC Study) and The Diabetes Mellitus and Vascular Health Initiative (DMVhi) screening study." (PMID 39685849, 2024). "Diabetes mellitus (DM) is a severe chronic illness that presents clinical challenges worldwide characterized by hyperglycemia and glucose intolerance, which arise from insufficient insulin production by the pancreas or inefficient insulin utilization by the body." (PMID 39633380, 2024). "She explained that the reason for that was that when children are first diagnosed with diabetes, they start with the treatment using insulin injections, unlike adults who start on oral medications." (PMID 38336657, 2024). "Among these, three patients had diabetes mellitus that did not require insulin therapy, three were classified as obese, and six exhibited dyslipidemia." (PMID 39335658, 2024). "One potential explanation for the lack of quantifiable cytokine detection is that diabetes mellitus is a dynamic disorder with expected changes in the inflammatory milieu from the time of diagnosis to various time-points after institution of insulin therapy." (PMID 39234180, 2024). "As pancreatic β cells are the sole producers of insulin in the body, their death leads to a complete absence of insulin secretion, ultimately resulting in the development of diabetes." (PMID 38167106, 2024). "Longer duration of diabetes or duration of insulin therapy are not obstacles to a successful switch." (PMID 38792590, 2024). "We included 47 people with type 1 diabetes, 15 with insulin-treated type 2 diabetes, and 32 controls without diabetes." (PMID 38376580, 2024). "Diabetes disrupts glucose metabolism, resulting in a negative energy balance, especially during insulin shortage." (PMID 39251658, 2024). "In individuals with diabetes, the most frequently prescribed class of anti-diabetic drug was DPP-4 inhibitors, the second-most frequently prescribed drug was SU or glinides, and the third-most frequently prescribed drug was insulin." (PMID 38592103, 2024). "Access to affordable insulin is crucial, yet access to self-monitoring blood glucose (SMBG) devices (e.g., meters, strips, lancets, continuous monitoring systems) is also pivotal for diabetes management." (PMID 39361609, 2024). "Regarding signs of ketoacidosis (DKT-15), 4.4% of insulin treated patients gave a correct answer." (PMID 38525337, 2024). "As GLP-1RA and basal insulin are not first-line therapies, the proportion of users gradually increased with time since diabetes diagnosis." (PMID 38175642, 2024). "The most prevalent type of diabetes, type 2 diabetes (accounting for 90% of cases), affects adults and occurs when the body becomes resistant to insulin or does not produce enough of it." (PMID 39995445, 2024). "Information on other glucose related factors, diabetes medications, and insulin levels, were not available." (PMID 38419016, 2024). "In insulin-resistant conditions, such as diabetes, the trafficking of GLUT4-containing vesicles is impaired, and the increase in GLUT4 expression and/or its translocation to the cell surface is a primary target in the treatment of diabetes." (PMID 38279251, 2024). "Virtual games for children’s diabetes education include Balance33 and the Android game Huima Hiilari, in which the player can jump and run whilst monitoring blood glucose, taking insulin injections, and choosing foods." (PMID 38193465, 2024). "Diabetes was managed using oral glucose-lowering drugs or glucagon-like peptide 1 agonists, with no patient requiring insulin therapy." (PMID 38532073, 2024). "The 3 main kinds of diabetes are type 1, an autoimmune disease in which the body stops producing insulin; type 2, where the body stops using insulin well and can no longer regulate normal glucose levels; and gestational diabetes, which occurs during pregnancy." (PMID 38530352, 2024).
diabetes (continued). "Furthermore, recent research provides support for the connection between type 2 diabetes mellitus (T2DM) and neurodegeneration through two key factors: the increase in proinflammatory cytokines and the onset of insulin/IGF-1 resistance." (PMID 38300646, 2024). "Type 2 diabetes mellitus (T2DM), a prevalent metabolic disorder, arises from two primary factors: impaired insulin secretion by pancreatic β-cells and the reduced responsiveness of insulin-sensitive tissues to insulin." (PMID 39200096, 2024). "Additionally, in male Wistar rats with diabetes induced by streptozotocin (STZ), GA improved pathological alterations in pancreatic islet cells, promoted β-cell regeneration, and boosted insulin output." (PMID 39840111, 2024). "These variables comprised LVEF, estimated Glomerular Filtration Rate (eGFR), fasting blood glucose levels, duration of diabetes mellitus (DM), history of previous coronary artery disease (CAD), TG levels, usage of oral anti-hyperglycemic agents, and insulin therapy." (PMID 38978967, 2024). "Of interest, a patient with KCNJ11-TNDM with diabetes onset in 2022 entered remission without any insulin or sulfonylurea treatment, confirming an observation we made in 2 other patients with TNDM associated with KCNJ11 pathogenic variants." (PMID 38408297, 2024). "Participants with shortened diabetes periods and those who received no treatment with insulin had a greater probability of BTC." (PMID 39410050, 2024). "The goal of modern diabetes technology is the development of an automated insulin delivery system that attempts to replace the lack of insulin in diabetic patients in a manner that mimics endogenous insulin secretion." (PMID 39065641, 2024). "In one study trying to implement pharmacists in primary care to assist with diabetes support to enhance insulin prescribing, they found the intervention to not be successful due to the need for providers to change their routines to implement the services." (PMID 39195848, 2024). "In this model, diabetes originates from abnormalities in insulin signaling rather than from insufficient insulin secretion." (PMID 38448948, 2024). "It is defined as a form of diabetes mellitus characterized by high blood glucose, insulin resistance and a relative lack of insulin." (PMID 39514611, 2024). "In our cohort of patients, none developed diabetes or sustained hyperglycemia requiring insulin administration." (PMID 38189960, 2024). "While exogenous insulin is not a cure, efforts are underway to reverse autoimmunity during diabetes using immunomodulatory therapies." (PMID 38515175, 2024). "The pharmacotherapeutic approaches of the various diabetes models evaluated, including the use of insulin and non-insulin agents like aminoguanidine, Voglibose, sitagliptin, exenatide, and metformin, reveal conflicting short-term outcomes." (PMID 39723258, 2024). "Furthermore, quercetin improved plasma insulin levels and lowered blood glucose in streptozotocin (STZ)-induced diabetes model by maintaining β-cells, thereby enhancing the effect of serum insulin." (PMID 38474512, 2024). "In T2DM, the body does not produce enough insulin for proper function, or the cells in the body do not react to insulin (insulin resistance), and approximately 90% of all cases of diabetes worldwide are T2DM." (PMID 39083503, 2024). "Diabetes control was worse in DFS+ than DFS− patients (HbA1C 60.8 ± 19 vs. 55.3 ± 16.6 mmol/mol) (p: 0.009) despite the more frequent use of insulin (74.2% vs. 45.1%) and more intensive insulin regimens (basal bolus regimen 73.0% vs. 53.5%)." (PMID 38592270, 2024). "As the cohort of patients interviewed in this study had shown a lack of understanding of the definition of diabetes and its types, as well as the types of insulin available and their varying effects, these were incorporated into the initial part of the module." (PMID 38694587, 2024).